LINC00221 (long independently transcribed non-coding RNA 221)
Synonyms: C14orf98; NCRNA00221
Gene: Long non-coding RNA gene on chromosome 14 (106,482,435 to 106,521,073, forward strand). Ensembl gene ENSG00000270816.
Diseases named in the same sentence as LINC00221 in open-access papers:
LINC00221 is named in the same sentence as 7 diseases in open-access papers, as found by Europe PMC text mining. Sharing a sentence is not in itself a finding about the gene and the disease. The quoted sentences say what the papers report.
breast carcinoma (1 paper, 2020). "TANRIC analysis indicated that ER positive breast cancer patients with higher expression of LINC00221 have a higher survival probability (p = 0.03)." (PMID 33324567, 2020).
tumor (2 papers, 2019 to 2021). "Analysis by RT-qPCR demonstrated noticeably higher expression of LINC00221 in the HCC tissues versus adjacent non-tumor tissues." (PMID 33836753, 2021). "LINC00221 was involved in ceRNA networks in several tumor types." (PMID 31007608, 2019). "The expression of LINC00221 was markedly reduced in the tumor xenografts of nude mice transplanted with LINC00221-deficient Huh7/MHCC97-H cells, while its expression was considerably elevated in the tumor xenografts of mice transplanted with Huh7/MHCC97-H cells overexpressing LINC00221." (PMID 33836753, 2021).
cancer (1 paper, 2021). A tumor composed of atypical neoplastic, often pleomorphic cells that invade other tissues. "Therefore, silencing LINC00221 could inhibit cancer progression in HCC cells." (PMID 33836753, 2021).
LINC00221 also shares sentences with these, for which no sentence is quoted: hepatocellular carcinoma (2 papers); acute lymphoblastic leukemia (1); gastric cancer (1); neuroblastoma (1).